CD44 (CD44 molecule (IN blood group))
Diseases named in the same sentence as CD44 in open-access papers (continued):
Sharing a sentence is not in itself a finding about the gene and the disease.
ovarian carcinoma (continued). "Targeting CD44 in the ovarian cancer should be attributed to targeting the CSC population, since overexpression of CD44 in SK-OV-3 could correlate with CSC–like character." (PMID 30818864, 2019). "FAM-IL could successfully allow FAM uptake in the CD44 positive ovarian cancer in one hour exposure of FAM-IL." (PMID 30818864, 2019). "In this study, we designed a drug-delivery system targeting ovarian cancer overexpressing CD44." (PMID 30818864, 2019). "We then observed the effect of CD44 siRNA on the growth, migration and invasion of ovarian cancer." (PMID 31497537, 2019). "Collectively, CD44 could be a suitable candidate of target molecule in ovarian cancer to apply drug delivery and minimize side effects." (PMID 30818864, 2019). "Our study suggested that CD44 may serve as a prognostic marker as well as possible treatment target for ovarian cancer." (PMID 31497537, 2019). "Clarifying the role of CD44 in the prognosis of ovarian cancer may be of great help for the development of novel treatment strategies." (PMID 31497537, 2019). "Also, as discussed here below, ovarian cancer exosomes containing the Wnt target and transmembrane protein CD44 have been shown to participate in the formation of pre-metastatic niches." (PMID 31614568, 2019). "However, the exact role of CD44 in EMT in ovarian cancer remains elusive and requires further investigation." (PMID 31497537, 2019). "Presumably, up-regulation of Caveolin-1 in CD44 knockdown ovarian cancer cells may partially contribute to the favorable prognosis of ovarian cancer patients." (PMID 31497537, 2019). "In addition, ovarian cancer cells’ exosomes encompassing the cell-surface glycoprotein CD44 can transfer it to peritoneal mesothelial cells and induce their reprogramming by EMT activation." (PMID 31614568, 2019). "Intriguingly, using an ovarian cancer xenograft model, they showed that paclitaxel treatment promotes the enhanced expression of CD44 in recurrent tumors, indicating that a subpopulation of CD44-positive cancer cells possesses the ability to increase chemotherapy resistance at metastatic sites." (PMID 31261739, 2019). "Additionally, HE4 expression in ovarian cancer tissues positively correlated with the adhesion molecules CD44, integrin β1, and integrin α5." (PMID 31210752, 2019). "CD44, CD24, CD133, CD117, and EPCAM have been reported to be associated with ovarian cancer." (PMID 30581772, 2018). "Cells are positive for EpCAM, CK19, and CD44; they have relatively low plating efficiency/ability to form spheroids, a low migration rate, and intermediate invasiveness in matrigel, as compared to other ovarian cancer lines." (PMID 30018258, 2018). "One study was carried out using a cell population CD44+MyD88+ enriched in epithelial ovarian cancer stem cells: this cell population exhibits multiple properties of ovarian cancer stem cells, including chemoresistance and the property to differentiate into multiple cell types." (PMID 29389895, 2018). "CD44 is a receptor for hyaluronic acid,up-regulation of CD44 represents a crucial event in the development of metastasis, recurrence, and drug resistance to current treatments in ovarian cancer." (PMID 28679402, 2017). "Although the association between the expression of CD44 or its isoforms and the survival of patients with ovarian cancer has been well investigated, the prognostic values of CD44, CD44s, and CD44v6 in predicting the survival of patients with ovarian cancer remains controversial." (PMID 28070170, 2017). "Detection of CD44 may be an effective tool for pathological diagnosis and prognostic prediction of ovarian cancer patients in clinical applications." (PMID 28070170, 2017). "CD44 has recently been reported as a cancer stem cell marker in ovarian cancer." (PMID 28070170, 2017). "In addition, some CD117+CD44+ ovarian cancer stem cells overexpress HOTAIR, and silencing HOTAIR with siRNA impaired the migration and invasion of ovarian cancer stem cells." (PMID 28649178, 2017).
ovarian carcinoma (continued). "Among these CSC markers, CD44 is the most frequently reported in ovarian cancer." (PMID 28070170, 2017). "Next, we analyzed the impact of CD44 expression on the survival of ovarian cancer patients." (PMID 28070170, 2017). "However, the clinicopathological and prognostic value of this marker in ovarian cancer remains controversial; Here, we aimed to investigate the correlation between CD44 expression and the clinicopathological features or survival of ovarian cancer patients." (PMID 28070170, 2017). "Although some studies reported that high levels of CD44 expression was associated with a poor prognosis in ovarian cancer patients, On the contrary, other groups concluded that CD44 expression had no influence on the survival of patients with ovarian cancer." (PMID 28070170, 2017). "ONCOFIDTM-S is a conjugate of HA with SN38 (7-ethyl-10-hydroxycamptothecin) and studies have demonstrated that it showed higher anti-proliferative in-vitro activity compared to free SN38 when used against colon, gastric, breast, oesophageal, lung, and ovarian cancer cells, which overexpress CD44." (PMID 27825361, 2016). "In ovarian cancer, CD44+/MYD88+expression denotes stem-like property and chemoresistance." (PMID 27655682, 2016). "However, little is known about the alteration of CD44 expression in recurrent ovarian cancer during chemotherapy." (PMID 25823654, 2015). "Therefore, it has been established that ovarian cancer cell adhesion to mesothelial cell monolayers is mediated, at least in part, by the interaction between HA and CD44." (PMID 26569327, 2015). "Immunohistochemistry analysis of HA-PEI/HA-PEG/MDR1 siRNA CD44 targeted nanoparticle on Pgp staining in ovarian cancer MDR tumor tissues further confirmed downregulation of Pgp as compared with either saline alone, MDR1 alone or HA-PEI/HA-PEG/non-specific siRNA nanoparticle treatment." (PMID 25687880, 2015). "Thus, up-regulation of CD44 represents a crucial event in the development of metastasis, recurrence, and drug resistance to current treatments in ovarian cancer." (PMID 25823654, 2015). "Immunofluorescence studies further confirmed that CD44 could be detected in both sensitive and resistant cells and in ovarian cancer tissues." (PMID 25687880, 2015). "The present study provided the first evidence that human SKOV3 CD117+ CD44+CSC-based vaccine may induce the anti-ovarian cancer immunity against tumor growth by reducing the CD117+CD44+CSC population." (PMID 26497895, 2015). "Developing strategies to target CD44 may prevent metastasis, recurrence, and drug resistance in ovarian cancer." (PMID 25823654, 2015). "The CD44 molecule is also physically linked with the product of the HER-2/neu oncogene —tyrosine kinase and EGF receptor, the expression of which predict poor prognosis in breast and ovarian cancers, and in 9 % of ECs (but in 27 % of metastatic ECs)." (PMID 25129125, 2015). "These positive consistent data allows us suppose that our developed SKOV3 CD117+CD44+CSC vaccine induced anti-ovarian cancer efficacy that is related with the diminution of CD117+CD44+CSC as well as ALDH-positive cell populations by eliciting effective immunity in the athymic nude mouse model." (PMID 26497895, 2015). "CD44 plays crucial roles in ovarian cancer cell growth, migration, and invasion." (PMID 25823654, 2015). "Induction of CD44 expression has been addressed during the progression of ovarian cancer." (PMID 25823654, 2015). "CD44 has also been shown to mediate ovarian carcinoma cell adhesion to peritoneal mesothelial cells, while other in vivo studies have suggested that CD44s is required for human ovarian cancer cell adhesion to mesothelial cell surface HA." (PMID 26569327, 2015). "DLX4, therefore, might contribute to poor outcomes in ovarian cancer, in part, by promoting peritoneal implantation of tumor cells via enhanced CD44 expression and tumor-mesothelial cell interactions in an NF-κB-dependent manner." (PMID 26569327, 2015).
ovarian carcinoma (continued). "The principal molecule among these is HA; when CD44 on the surface of ovarian cancer cells binds to HA on mesothelial cells, this combination may trigger peritoneal metastasis." (PMID 25823654, 2015). "In addition, miR-199a-5p also targets CD44 to suppress tumorigenicity and multidrug resistance in ovarian cancer initiating cells." (PMID 25839163, 2015). "Most importantly, the effect of chemotherapy treatment on CD44 expression in ovarian cancer is also unknown." (PMID 25823654, 2015). "Consequently, our investigations demonstrated that high expression of CD44 predicts an unfavorable prognosis in ovarian carcinoma." (PMID 25823654, 2015). "Moreover, the CSC-based vaccine significantly reduced the CD117+CD44+CSC as well as the aldehyde dehydrogenase 1 positive cell populations in the ovarian cancer tissues in the xenograft mice." (PMID 26497895, 2015). "CD44 is overexpressed in drug resistant ovarian cancer cell lines; therefore, we examined whether disruption of CD44 expression would influence the function of SKOV-3TR and OVCAR8TR." (PMID 25823654, 2015). "Few studies have investigated CD44 expression in ovarian cancer patients with long-term follow up." (PMID 25823654, 2015). "Moreover, dependence of CD44 on versican, a large HA-binding proteoglycan, has been shown in ovarian cancer where HA and versican form a pericellular matrix around CD44-expressing ovarian cancer cells that further promotes their motility and invasion in vitro." (PMID 26569327, 2015). "In this study, we first wanted to know whether the SKOV3 CD117+CD44+CSC vaccine would elicit an immune response against SKOV3 ovarian cancer in nude mouse model." (PMID 26497895, 2015). "As we reported recently, stable knocking down CD44 by lentivirus-based CD44 shRNA could increase sensitivity to paclitaxel in ovarian cancer cells." (PMID 26079799, 2015). "Additionally, CD44 knockdown in ovarian cancer cells increased sensitivity to the anticancer drug paclitaxel." (PMID 27600234, 2015). "In addition, CD44 knockdown ovarian cancer cells increased sensitivity to the anticancer drug paclitaxel." (PMID 25823654, 2015). "In addition, previous studies have shown that in ovarian cancer cells, paclitaxel-HA conjugate interacted with CD44, entered the cells through a receptor-mediated mechanism, and exerted a concentration-dependent inhibitory effect on tumor cell growth." (PMID 25687880, 2015). "Using a highly aggressive and metastatic ovarian cancer cell line (HEY) which sustains high endogenous expression of Oct4A, we show that suppression of Oct4A resulted in the loss of CSC-associated expression of Lin28, Sox-2, EpCAM and CD44." (PMID 26260289, 2015). "In EOC, we and others have shown that CD44+/MyD88+ epithelial ovarian cancer stem cells (EOC stem cells) possess tumor-initiating properties and exhibit diverse resistance to a wide-range of chemotherapy agents including, but not limited to, platinums and taxanes." (PMID 25237928, 2014). "Furthermore, CD44 expression level of ovarian cancer cells is inversely proportional to patient survival." (PMID 24739440, 2014). "Our previous study has shown that ovarian cancer may be initiated by ovarian cancer initiating cells (OCIC) characterized by surface antigen CD44 and c-KIT (CD117)." (PMID 25545504, 2014). "Similarly, a CD24+/CD44+ cancer stem cell subpopulation has been identified in solid tumors and cancer cell lines in both colorectal and ovarian cancers." (PMID 24612587, 2014). "All three ovarian cancer cell lines were shown to express both CD44 and CD168." (PMID 24739440, 2014). "Lewis y antigen and CD44 molecule expression levels in different histotype of ovarian carcinoma." (PMID 23468946, 2013). "The same research group identified bipotent CD44+ CD34− cells in ovarian cancer and demonstrated that, in addition to being capable of tumor regeneration, these cells also contribute to tumor vascularization by a mechanism that involves inhibitor of kappa-kinase beta (IκK-β)." (PMID 23782518, 2013).
ovarian carcinoma (continued). "Although the effects of alternative splicing and post-translational glycosylation of CD44 on its interaction with HA have been widely studied in recent years, few reports have described the effects of alterations in fucosylation on CD44-dependent CAM-DR of ovarian cancer cells." (PMID 23468946, 2013). "Furthermore HA treatment significantly increased the expression of ABC drug transporters (ABCB3, ABCC1, ABCC2, and ABCC3), but only in ovarian cancer cells expressing CD44." (PMID 24124770, 2013). "Therefore, to address this question, in the present study, we have quantified ovarian cancer drug resistance and expression of Lewis y antigen and CD44 in tissues from ovarian cancer patients." (PMID 23468946, 2013). "We used two subtypes of ovarian cancer cells based on their expression of CD44 and MyD88." (PMID 24403249, 2013). "In CD44+MyD88+ ovarian CSC/TICs from either ovarian cancer tissues or ovarian ascites, hypoxia/HIF-1 is an extracellular signal that may initiate differentiation of CSC/TICs by triggering TWIST1 expression." (PMID 23528891, 2013). "In our preliminary studies, we have found that, although CD44 mRNA levels were similar in α1,2-fucosyltransferase transfected ovarian cancer cells (RMG-1-H) and the parent cells (RMG-1), CD44 protein expression levels were significantly higher in the RMG-1-H cells." (PMID 23468946, 2013). "Indeed in ovarian cancer, CD44+CD117+ spheroids were resistant to chemotherapy and were able to initiate and propagate tumors in mice." (PMID 23484135, 2013). "Thus, it is not surprising that stemness properties have been reported in ovarian cancer cells that have been isolated using a variety of cell surface markers, such as CD44, CD133, and CD24." (PMID 24403249, 2013). "Further work in the area of chemo-resistant ovarian cancer has demonstrated that CD44+ ovarian cancer stem cells represent a small proportion of cancer cells capable of sustaining tumor growth and chemo-resistance and these cancer stem cells highly express genes encoding claudin-4." (PMID 23685873, 2013). "It is known that cancer stem cells residing in epithelial ovarian cancers can be CD133+ or CD44+ subpopulation cells and these specific markers may be potential therapeutic targets in this devastating disease." (PMID 22642602, 2012). "Therefore, our results verify that hypoxia significantly increases the expression of CD44, and CD44bright cells possess significantly higher stem-like properties in the ovarian cancer cell lines OVCAR-3 and ES2." (PMID 22642602, 2012). "HA increases the adhesion of CD44-expressing ovarian cancer cells to peritoneal cells in vitro." (PMID 23109879, 2012). "The formation of a stabilized HA/versican pericellular matrix surrounding ovarian cancer cells, protects the ovarian cancer cells against the mechanical forces in the peritoneal cavity and enables strong ovarian cancer cell adhesion to CD44 expressed by peritoneal cells." (PMID 21541039, 2011). "Lewis y antigen strengthens CD44-mediated adhesion and spreading of ovarian cancer cells." (PMID 21294926, 2011). "Notably, most cells stained for EpCAM, CD44, and vimentin, suggesting that EpCAM/CD44 signals underestimate the phenotypic diversity within early passage ovarian cancer cells." (PMID 21264259, 2011). "However, our findings show that in early-stage ovarian cancer, patients with tumors containing >20% CD44+ EOC stem cells had a shorter progression-free survival compared to patients with tumors having <20% of these cells." (PMID 21904548, 2011). "Indeed, it has been demonstrated that peritoneal cells produce both extracellular matrix molecule, hyaluronan (HA) and the HA receptor, CD44, and can promote ovarian cancer motility by increasing their HA production in co-culture with ovarian cancer cells." (PMID 21541039, 2011).
ovarian carcinoma (continued). "The objectives of the present study were twofold: (i) to characterize the location of CD44+ EOC stem cells in tissue samples and (ii) to determine whether the CD44+ EOC stem cell “load” correlates with clinical parameters in ovarian cancer patients." (PMID 21904548, 2011). "In support of this idea, the expression of CD44 is reduced in the high grade ovarian cancers, and the released hyaluronan could be trapped in the stroma by complexing with versican." (PMID 19435493, 2009). "The large variation of the CD44 expression from study to study may be attributed to the different methodologies used in the assessment of CD44 expression or to the different stages of ovarian cancer in the analysis." (PMID 19603017, 2009). "In 96 ovarian cancer patients, the present study investigates the clinical significance of pretreatment concentrations of soluble CD44 standard (CD44s) and its isoforms v5 and v6 determined in the serum and the ascitic fluid by means of recently developed enzyme-linked immunosorbent assays (ELISAs)." (PMID 9413956, 1997). "Furthermore, CD44 serum concentrations in the ovarian cancer patients were compared with circulating CD44 levels in 50 healthy age-matched female blood donors." (PMID 9413956, 1997). "Moreover, CSCs coexpressing CD117 and CD44 exhibit chemoresistance in ovarian cancer." (PMID 39919692, 2025). "However, among the overlapped DE genes, we identified upregulation of genes encoding several markers typically overexpressed in ovarian cancer: cyclin E1 (Ccne1), RAD51-associated protein 1 (Rad51ap1), osteopontin (Spp1) and its signaling receptor, Cd44." (PMID 40642792, 2025). "Moreover, CD44 expression was observed in patients with chemotherapy-resistant ovarian cancer." (PMID 38201468, 2023). "We could speculate that TMEM2 could be extremely important in cancers with a pericellular coat made of HA, for example in ovarian cancer, where this localization “suggests a pivotal role of the CD44-HA signaling axis for malignant progression in ovarian cancer”." (PMID 36765756, 2023). "The non-kinase transmembrane receptor CD44 represents a promising therapeutic target for ovarian cancer treatment, as it has been implicated in the development of chemoresistance, maintenance of cancer stem cells, and promotion of metastatic progression through diverse mechanisms." (PMID 37284314, 2023). "In addition, our survival analysis showed that CD44 expression is slightly associated with a better prognosis for ovarian cancer cases and for the PD-L1 negative ovarian cancer (HR = 1.6, 95% CI [0.7–3.7] and (HR = 2.4, 95% CI." (PMID 36604635, 2023). "Moreover, glycosylation of CD44 could control HA adhesion, as demonstrated in ovarian cancer, amplifying or inhibiting attachment of CD44 to HA." (PMID 33889547, 2021). "Interestingly, a recent study demonstrated that ovarian cancer-derived exosomes could transfer CD44 to human peritoneal mesothelial cells (HPMCs) and induce morphologic change in HPMCs to a mesenchymal, spindle phenotype." (PMID 34680456, 2021). "Collectively, CD44 could be a promising target molecule for immunotherapy in ovarian cancer." (PMID 34680456, 2021). "CD44 may be a potential therapeutic approach for ovarian cancer." (PMID 33627162, 2021). "Collectively, these data may inspire a new wave of clinical investigation that will provide important insights into the clinical benefits of eliminating immunosuppression and preventing therapy resistance of ovarian cancer by targeting the CD44/STAT3 axis in different TME resident cell types." (PMID 33335857, 2020). "Given that both CD44 and STAT3 are strongly implicated in the metastatic progression and chemoresistance of ovarian tumors, this review summarizes currently available evidence about functional crosstalk between CD44 and STAT3 in human malignancies with an emphasis on ovarian cancer." (PMID 33335857, 2020).